PHB2 (prohibitin 2)
Diseases named in the same sentence as PHB2 in open-access papers (continued):
Sharing a sentence is not in itself a finding about the gene and the disease.
hepatocellular carcinoma (11 papers, 2018 to 2026). A malignant tumor that arises from hepatocytes. "Conversely, in NSCLC and hepatocellular carcinoma, PHB2 promotes tumorigenesis by supporting cell survival and migration." (PMID 38200519, 2024). "A publication on hepatocellular cancer by the Xiang group reported PHB2 as a key player in PINT87aa-induced cancer senescence." (PMID 37190120, 2023). "In both colon and hepatocellular cancer, a novel mechanism of miR-34a inhibition was reported where Lnc34a recruits PHB2 to repress miR-34a." (PMID 37190120, 2023). "A previous study of hepatocellular carcinoma suggested that the binding of Nrf2 and prohibitin 2 (PHB2) is required for efficient expression." (PMID 36505409, 2022). "It has been reported that commonly up-regulated PHB2 has been found in certain tumors, such as esophageal squamous cell carcinoma (ESCC), non-small cell lung cancer (NSCLC), and hepatocellular carcinoma, and PHB2 is considered as a prognostic marker for ESCC and NSCLC." (PMID 36658121, 2023). "In hepatocellular carcinoma, a long non-coding RNA-encoded peptide PINT87aa could induce cellular senescence by blocking FOXM1-mediated PHB2." (PMID 35646056, 2022). "Meanwhile, in hepatocellular carcinoma, PHB2 is required for cancer cell proliferation." (PMID 29367618, 2018). "In hepatocellular carcinoma (HCC), PHB2 promotes cell proliferation by aiding in the repression of miR-34a production." (PMID 37190120, 2023). "In hepatocellular carcinoma, Xiang and colleagues demonstrated the cancer-inhibitory activity of PINT87aa embedded in lncRNA LINC-PINT depending on its suppression of FOXM1-mediated PHB2." (PMID 38351332, 2024). "In hepatocellular carcinoma (HCC), the glycosyltransferase GALNT14 mediates O-glycosylation of PHB2, enhancing tumor cell proliferation, migration, and chemotherapy resistance through activation of the insulin-like growth factor 1 receptor (IGF1R) signaling cascade." (PMID 40868286, 2025).
heart failure (7 papers, 2018 to 2025). Inability of the heart to pump blood at an adequate rate to meet tissue metabolic requirements. "Ablation of PHB2 causes heart failure mainly through cardiac FAO disturbance and mitochondrial dysfunction." (PMID 32165613, 2020). "Our study demonstrates that cardiac-specific knockout of Phb2 leads to accumulation of lipid droplets and causes heart failure." (PMID 32165613, 2020). "Similarly, PHB2 deficiency is reported to impair cardiac fatty acid oxidation and cause heart failure." (PMID 40450326, 2025). "PHB2 deficiency causes heart failure, which is fatal in mice." (PMID 37371979, 2023). "In summary, cardiac PHB2 deficiency-induced mitochondrial dysfunction resulted in fatty acid metabolic disorder through downregulating CPT1b, which played a major role in the course of heart failure in Phb2 cKO mice." (PMID 32165613, 2020). "Herein, cardiac mitochondrial dysfunction caused by PHB2 deficiency might partially account for heart failure in Phb2 cKO mice." (PMID 32165613, 2020). "The ablation of cardiac PHB2 exhibits a more severe heart failure at an early age (50% mortality at day 70); however, haploinsufficiency of CPT1b mice showed heart failure only under a severe pressure-overload condition." (PMID 32165613, 2020). "Phb2 cKO mice exhibited severe heart failure and died at an average age 10 weeks, with cardiac lipid accumulation and mitochondrial dysfunction." (PMID 32165613, 2020). "Cardiac-specific Phb2 knockout mice exhibited severe heart failure shown by dilated left ventricles, interstitial fibrosis, and systolic dysfunction." (PMID 32165613, 2020). "Further studies on PHB2’s control of mitochondrial metabolic homeostasis will contribute to develop or optimize therapeutic approaches to heart failure." (PMID 32165613, 2020). "It was reported PHB2 deficiency could lead to impaired cardiac FAO, mitochondrial dysfunction and heart failure." (PMID 35844503, 2022). "Cardiac Phb2 cKO mice exhibited typical phenotypes of dilated cardiomyopathy and heart failure." (PMID 32165613, 2020). "In our study, we found that PHB2 deficiency in the heart impaired cardiac FAO and reduced ATP level, and that these defects in Phb2 cKO hearts occurred at 6 weeks of age, prior to the occurrence of heart failure which was evident at 8 weeks of age." (PMID 32165613, 2020). "In our study, we generated cardiac specific Phb2 knockout mice that exhibited fatty acid oxidation disturbance, mitochondrial dysfunction, and eventually heart failure and lethality, demonstrating that PHB2 is essential for maintaining normal cardiac metabolic functions." (PMID 32165613, 2020). "Thus, cardiac specific Phb2 knockout mouse model is generated and cardiac ablation of Phb2 results in heart failure shown by shortened lifespan, dilated left ventricle, interstitial fibrosis, and systolic dysfunctions." (PMID 32165613, 2020). "Whether the COMP–prohibitin 2 interaction in the heart plays essential roles in mitochondrial function and heart failure requires further investigation." (PMID 29867124, 2018). "In our study, by generating cardiac specific Phb2 knockout mice, we demonstrate that PHB2 deficiency significantly impairs cardiac fatty acid oxidation (FAO) and leads to mitochondrial dysfunction, and eventually results in severe heart failure at an earlier age." (PMID 32165613, 2020). "Considering the beneficial effects offered by PKM2 overexpression on heart failure and myocardial infarction, we asked whether SC may be alleviated by PKM2 through stabilizing PHB2 and supporting MQC in cardiomyocytes." (PMID 38856931, 2024). "A reduction in total PHB2 expression in cardiac-specific PHB2 knockout mice impairs myocardial fatty acid oxidation (FAO) and induces heart failure through suppressing carnitine palmitoyltransferase 1b (CPT1b), a rate-limiting enzyme of cardiac mitochondrial FAO." (PMID 38856931, 2024).
leukemia (7 papers, 2015 to 2024). A malignant (clonal) hematologic disorder, involving hematopoietic stem cells and characterized by the presence of primitive or atypical myeloid or lymphoid cells in the bone marrow and the blood. "Increased Phb2 phosphorylation at Ser91 has been found to inhibit mitochondria‐mediated apoptosis and therefore to favour human leukaemia progression." (PMID 39143739, 2024). "Meanwhile, experiments in leukemia cells showed that PHB2 phosphorylation at either S176 or S91 exerts anti-apoptotic actions by attenuating mitochondrial dysfunction." (PMID 38856931, 2024). "Both in vivo and in vitro, PHB2 was complexed with AKT in the nucleus of leukemia cells and phosphorylated during differentiation induced by all- trans retinoic acid (ATRA) treatment." (PMID 37190120, 2023). "Evidence is provided herein that PHB1 and PHB2 are overexpressed in a panel of leukemia and lymphoma cell lines compared to normal naïve PBMCs." (PMID 29029444, 2017). "Although prohibitins have been reported to localize to a variety of subcellular locations in tumor cells, PHB1 and PHB2 were shown to co-localize primarily to the mitochondria in Kit225 and leukemia/lymphoma patient tumor cells." (PMID 29029444, 2017). "In NB4 human leukemia cells, PHB2 is phosphorylated by Akt on Ser91 and Ser176, and dephosphorylation of PHB2 Ser91 results in rapid cellular apoptosis." (PMID 26091791, 2015). "For instance, it was shown that PHB2 phosphorylation at Ser91 promotes human leukemia cell progression through repressing mitochondrial apoptosis, whereas phosphorylation at Ser39 mediates PHB2 association with AURKA and MAP1LC3 to elicit Parkin-independent mitophagy." (PMID 39285950, 2022). "Indeed, PHB1 and PHB2 protein levels were overexpressed in tumor cells isolated from patients with leukemia and lymphoma compared to normal naïve PBMCs." (PMID 29029444, 2017). "Moreover, PHB1 and PHB2 protein levels were significantly higher in tumor cells isolated from leukemia and lymphoma patients compared to healthy donor PBMCs and localized to primarily to the mitochondria." (PMID 29029444, 2017). "Indeed, PHB1 and PHB2 protein levels were significantly higher in tumor cells isolated from leukemia and lymphoma patients compared to PBMCs from healthy donors." (PMID 29029444, 2017). "In leukemia, AKT1 and AKT2 phosphorylate PHB2 at S91, regulate nuclear-mitochondria activity, and further promote cell survival." (PMID 37190120, 2023). "A recent paper illustrated that, consistent with the proliferative function of PHB2 in leukemia cell lines, overexpression of PHB2 was correlated with adverse prognosis in cytogenetically normal acute myeloid leukemia (CN-AML patients)." (PMID 37190120, 2023). "There were many leukemia-related genes in the up-regulated genes of K1 group, such as UBB (P=1.56e-50), MIF (P=2.76e-50), DRAP1 (P=1.72e-49), RPS25 (P=1.9e-49), EIF3K (P=4.77e-49), SSNA1 (P=1.27e-48), GPX4 (P=3.01e-48), PHB2 (P=7.13e-48), NME2 (P=2.44e-47) or CFL1 (P=4.07e-47)." (PMID 36408189, 2022).
diabetes (6 papers, 2020 to 2025). "Early studies showed that PHB2 deficiency suppresses pancreatic β-cell function and, thus, promotes diabetes progression through inducing mitochondrial fragmentation." (PMID 39285950, 2022). "PHB2, also called B cell receptor-associated protein 37 (BAP37) and repressor of estrogen receptor activity (REA), is expressed in immune cells in specific diseases such as lipodystrophy, diabetes, immunodeficiencies, and muscular dystrophy/wasting." (PMID 40168274, 2025). "In the realm of mitochondrial biology, Prohibitin 2 (Phb2) emerges as a pivotal protein with profound implications in the pathophysiology of diabetes." (PMID 38818468, 2024). "In summary, the present work suggests that diabetes-induced PGAM5 overexpression contributes to DCM through PHB2 dephosphorylation, disrupting the stabilizing effect of PHB2 on MQS in cardiomyocytes." (PMID 39285950, 2022). "β-cell specific PHB2 knockout mice (β-PHB2 −/−) have dysfunctional mitochondria, enhanced β-cell death, and diabetes." (PMID 33354575, 2020). "Given Phb2's integral part in orchestrating mitochondrial dynamics and its nexus with essential metabolic pathways, it presents an intriguing prospect as a therapeutic conduit for managing diabetes." (PMID 38818468, 2024). "Deletion of Prohibitin-2 in β cells has been shown to impair insulin secretion and mitochondrial function, resulting in a progressive worsening of glucose tolerance, and it promotes the development of diabetes." (PMID 35298439, 2022). "In addition, PHB2 is often upregulated in cancer and diabetes." (PMID 40168274, 2025). "Both qPCR and western blotting showed that baseline cardiac PHB2 expression was not affected by either diabetes induction or cardiac-specific Pgam5 KO." (PMID 39285950, 2022).
Parkinson disease (6 papers, 2017 to 2024). A progressive degenerative disorder of the central nervous system characterized by loss of dopamine producing neurons in the substantia nigra and the presence of Lewy bodies in the substantia nigra and locus coeruleus. "Decreased PHB1 and PHB2 expression is associated with aging and age-associated diseases with known mitophagy impairment including Parkinson’s disease and Alzheimer’s disease." (PMID 36593241, 2023). "The reduction of PHB2 inhibits the binding of PHB2 to LC3, inhibits mitophagy, exacerbates the loss of dopaminergic neurons, and accelerates the progression of Parkinson’s disease." (PMID 39091635, 2024). "did not directly investigate the upstream‐downstream relationship between Nrf2 and PHB2, in a Parkinson's disease cell model, the protein expression of PHB2 showed a positive correlation with Nrf2 and was associated with oxidative stress." (PMID 38077250, 2023). "One study reported that the depletion of PHB2 decreased the interaction between PHB2 and LC3, resulting in reduced mitophagy and exacerbated loss of dopaminergic neurons in a Parkinson’s disease mouse model." (PMID 37958902, 2023). "Prohibitin and Prohibitin-2 appeared to be altered in the context of Parkinson’s disease in our analysis." (PMID 29267236, 2017). "Taken together, inhibition of PHB2 phosphorylation to enhance mitophagy may be a novel approach for the treatment of Parkinson's disease." (PMID 36406767, 2022). "The newly discovered mitochondrial inner membrane protein prohibitin 2 (PHB2) has been confirmed to be involved in mitophagy, but no report indicates that PHB2 is involved in mitophagy in Parkinson's disease." (PMID 36406767, 2022). "However, the phosphorylation outcomes and regulatory mechanisms of PHB2 have not been reported in Parkinson's disease." (PMID 36406767, 2022). "In our study, we found that STI 571 could prevent PHB2 tyrosine phosphorylation to improve mitophagy and reduce oxidative stress, which provided a basis for further testing STI 571 as a neuroprotective drug for Parkinson's disease." (PMID 36406767, 2022).
rhabdomyosarcoma (6 papers, 2014 to 2023). A rare aggressive malignant mesenchymal neoplasm arising from skeletal muscle. "Meanwhile, the downregulation of PHB2 also induced apoptosis and promoted differentiation in fractions of rhabdomyosarcoma cells and played a crucial role in the adhesion processes in the cell, thereby sustaining cancer cell propagation and survival." (PMID 34750284, 2022). "Here, we investigated the role of PHB2 in human rhabdomyosarcoma (RMS) RD cells and found substantial localization of PHB2 in the nucleolus." (PMID 29367618, 2018). "PHB2 in different subcellular localizations has distinct roles in tumorigenesis and progression, such as the pro-tumorigenic effect of PHB2 in the cytoplasm of NSCLC cells and plasma membrane of rhabdomyosarcoma (RMS) cells." (PMID 36658121, 2023).
virus infection (6 papers, 2014 to 2026). "Here, we present the current understanding of PHB1 and PHB2 in bacterial and viral infection based on the cellular localization of PHBs at the plasma membrane, mitochondria, and cytoplasm." (PMID 42311502, 2026). "These PHB2-edited cell clones are valuable tools for further investigation of the roles of PHB2 in insect cell biology, virus infection and virus-host interactions." (PMID 39049926, 2024). "Antibody-mediated inhibition of infection and siRNA mediated knockdown of PHB2 expression resulted in significant lowering of virus infection and subsequent virus production in both A. aegypti and A. albopictus cell lines (CCL-125and C6/36)." (PMID 32306962, 2020). "Consistent with molecular findings from experimental studies, it is conceivable that PHB2 is a mitochondrial receptor for parkin-mediated mitophagy in this spontaneous model of viral infection." (PMID 32751272, 2020). "Based on their role of apoptosis suppression, hosts needed to decrease the expression of these proteins to promote apoptosis and prevent virus infection when exposed to virus, and this explained the notable down-regulation of PHB2 and CRT at 48 hpi." (PMID 25502928, 2014). "Therefore, our study suggests that PHB2 is a mitochondrial receptor for parkin-mediated mitophagy in a spontaneous model of viral infection." (PMID 32751272, 2020). "Very likely, PHB2 and other prohibitins will represent the topics of specific interest in next future as further details in PHB2 biology will contribute to gain insights into unexplored mitophagy mechanisms and virus infections." (PMID 32751272, 2020). "A further exciting research area will be to highlight PHB2 as an important target which may be useful in diagnosis and therapy of PHB-dependent diseases, including viral diseases." (PMID 32751272, 2020).
acute kidney injury (5 papers, 2021 to 2025). Sudden and sustained deterioration of the kidney function characterized by decreased glomerular filtration rate, increased serum creatinine or oliguria. "In acute kidney injury, ALDH2 is Kla modified at K52, which exacerbates tubular damage and mitochondrial dysfunction via attenuating its interaction with prohibitin 2 (PHB2), thus facilitating the ubiquitin-proteasome-dependent degradation of PHB2." (PMID 41285721, 2025).
ovarian carcinoma (5 papers, 2014 to 2023). A malignant neoplasm originating from the surface ovarian epithelium. "In ovarian cancer cells, there is a view that PHB2 also causes an increase in mitochondrial biogenesis, which may be related to the signaling pathways of SIRT3, OPA1, and PHB2 proteins in camp, but the mechanism of how PHB2 mediates biogenesis is still unclear." (PMID 36348375, 2022). "In summary, the breakdown of the PHB2/STOML2 complex promotes apoptosis of ovarian cancer cells through the mitochondrial PHB2/OMA1/DELE1 pathway." (PMID 37190120, 2023). "Exploring the regulation of OMA1 by the PHB2/STOML2 complex will help to illustrate a potential mechanism of targeting mitochondria to increase the chemosensitivity of ovarian cancer cells." (PMID 35163244, 2022). "The increased level of PHB2 in OC, in addition to its role in resistance to apoptosis, could also be responsible for the stabilization of a sub-complex I, possibly contributing to the decrease in complex I activity in ovarian cancer tissue." (PMID 31547300, 2019). "PHB2 and STOML2 are both reportedly overexpressed and attributed to the mitochondrial function and apoptosis resistance in ovarian cancer." (PMID 37190120, 2023). "Exploring other proteases that bind to the PHB2/STOML2 complex will provide more in-depth mechanistic insights into the roles of PHB2 and STOML2 in mitochondrial homeostasis and chemosensitivity of ovarian cancer." (PMID 35163244, 2022). "Therefore, exploring the relationship between the sublocalization of PHB2 and STOML2 and their functions will help to further illustrate their roles in the chemosensitivity of ovarian cancer." (PMID 35163244, 2022). "PHB2 and STOML2 are reportedly overexpressed in ovarian cancer, which is related to mitochondrial function and apoptosis resistance, but the mechanism remains unclear." (PMID 35163244, 2022). "Collectively, our results showed that the mitochondrial PHB2/OMA1/DELE1 pathway cooperated with cisplatin-induced ER stress to amplify the pro-death signals of MIM and MOM, which provided a novel mechanism for increasing the sensitivity of ovarian cancer to cisplatin." (PMID 35163244, 2022). "The ovarian cancer cell lines used in the present study express prohibitin-2 (results not shown), so it would be of interest to determine whether this protein is involved in the migratory responses observed in the present study." (PMID 25601855, 2014). "We highlight, in the heterogeneity of ovarian cancer, a characteristic “mitochondrial signature”, characterized by increased mitochondrial biogenesis and altered mitochondrial structure that could result from the cooperation of cAMP pathway and the SIRT3, OPA1, and PHB2 proteins." (PMID 31547300, 2019).